IFNG (interferon gamma)
Diseases named in the same sentence as IFNG in open-access papers (continued):
Sharing a sentence is not in itself a finding about the gene and the disease.
bacterial infection (422 papers, 2005 to 2026). "The ability of macrophages to kill many bacterial species is augmented by IFNγ treatment, and both mice and humans who lack proper IFNγ activity are susceptible to recurrent and sometimes fatal bacterial infections." (PMID 33684179, 2021). "IFNγ increases susceptibility to secondary bacterial infection by promoting inflammation and damage in the upper respiratory tract through both the ligand IFNγ and IFNγ receptor." (PMID 30619303, 2018). "Type I IFNs can dampen macrophage responsiveness to IFNγ and are associated with increased susceptibility to numerous bacterial infections." (PMID 28542482, 2017). "Type I IFNs regulate T cell production of IFNγ in a highly context-dependent manner, whereby type I IFNs are associated with enhanced IFNγ during extracellular bacterial infection, but with reduced IFNγ in response to intracellular pathogens." (PMID 27621733, 2016). "The expression of IFNγ, IL-27 and TNFα are all increased in sputum from steroid-resistant neutrophilic asthma patients where viral and bacterial infections have been implicated in exacerbations and disease progression." (PMID 27657907, 2016). "Specifically, type 1 eosinophils are activated in vitro with IFNγ and/or bacterial products, are present in the gastrointestinal tract at baseline, and expand with models of bacterial infection or chemical colitis." (PMID 41050650, 2025). "In bacterial infection, the canonical model for type 1 immunity is that IFNg signaling to macrophages increases their cell-autonomous killing capacity, thereby restricting intracellular pathogen replication." (PMID 40568097, 2025). "To test the requirement for MAPL in pyroptotic cell death we isolated primary BMDMs from WT and MAPL−/− mice and treated them with LPS and IFNγ to mimic bacterial infection and induce pyroptosis." (PMID 41083601, 2025). "On the other side, IFNγ is a crucial modulator of immunity to intracellular microbes and is robustly induced upon bacterial infection." (PMID 38671876, 2024). "IFNγ serves to recruit and activate macrophages, promoting granuloma formation and the inflammatory process during bacterial infection." (PMID 39676887, 2024). "Chronic IFNγ signaling, typically induced in the setting of bacterial infection, can compromise both of these barriers and is therefore an important driver of IBD pathogenesis." (PMID 38962090, 2024). "TAK981 treatment did not affect blood urea nitrogen but increased the innate immune responses to bacterial infection including serum IFNγ and TNFα levels." (PMID 37520526, 2023). "Here we examine the role of ongoing IFNγ responses to pre-established bacterial infection on SARS-CoV-2 disease outcomes in two murine models." (PMID 38086794, 2023). "Another cytokine of interest in bacterial infections with neurological symptoms, in this case for its proposed homeostatic functions, is interferon gamma (IFNγ)." (PMID 36915214, 2023). "Alternatively, to mimic a bacterial infection using LPS, microglia can be challenged in vitro using IFNγ to mimic a Th1 cell response or PolyIC to mimic an anti-viral response." (PMID 36745631, 2023). "Interferon-gamma is important for fighting bacterial infections as it activates macrophages, aiding in the elimination of intracellular pathogens." (PMID 37937155, 2023). "Within draining lymph nodes, NK cells significantly contribute to the early innate response against bacterial infections by producing interferon-gamma (IFN-γ)." (PMID 37764968, 2023). "IFNγ is a key mediator of immunity to intracellular microbes and is strongly induced upon bacterial infection." (PMID 38086794, 2023). "GBP1 acts a gatekeeper of microbe-induced macrophage apoptosis and pyroptosis, and IFNγ enhanced macrophage pyroptosis mediated by caspase-4 in a GBP1-dependent manner during bacterial infection, such as Shigella flexneri and Salmonella." (PMID 35682857, 2022).
bacterial infection (continued). "Epithelial cells treated with IFNγ-stimulated macrophage conditioned media rapidly reduce accessible cholesterol to protect against bacterial infection by preventing cholesterol-mediated transport between cells." (PMID 35959888, 2022). "In many protozoan and bacterial infections, the role of IL-10 in limiting IFNγ expression is critical for host survival, suppressing damaging immunopathology." (PMID 35428872, 2022). "Clearly, further studies are needed to identify the cell type involved in IL-15-dependent IL-15Rα-independent early IFNγ production following bacterial infection." (PMID 34956227, 2021). "Our data suggest that EBST enables host to rapidly produce Th1 derived cytokines—IFNγ and TNFα, in response to the virulent bacterial infection." (PMID 33861743, 2021). "As expected, bacterial infection induced a systemic inflammatory response characterized by increased plasmatic levels of TNFα, IL-6, IL-12, IFNγ and KC/GRO (CXCL-1) compared to PBS-treated mice." (PMID 34437647, 2021). "The lack of increase in microbicidal activity against Bc in macrophages stimulated with IFNγ was surprising, especially considering the extensive literature showing IFNγ-based bacterial killing in multiple bacterial infection systems." (PMID 33684179, 2021). "This resulted in an overall stronger IFNγ immune response against intracellular bacterial infection." (PMID 34222462, 2021). "Certainly, one of the primary roles of adaptive immunity, in the context of bacterial infection, is the production of IFNγ, the sole type II IFN, which stimulates the upregulation of various antimicrobial pathways in macrophages." (PMID 33684179, 2021). "BMMs that are mobilized in response to bacterial infections within peripheral tissues are known to be potent inducers of pro‐inflammatory interferons (eg, IFNγ), as well as additional cytokines and chemokines such as IL‐1, IL‐18, Ccl3, Cxcl9, and others." (PMID 32841534, 2020). "During intracellular bacterial infection, miR-29a-3p expression inversely correlates with IFNγ production." (PMID 32987746, 2020). "Neutrophils release IFNγ in response to IL-12 secretion, and excessive release of IL-12 and INFγ has been suggested to impair the response to bacterial infection." (PMID 32117109, 2020). "It was later reported that expansion of HSPCs (LSK cells) triggered by intracellular bacterial infection is mainly mediated by IFNγ." (PMID 32373117, 2020). "Triggering the apoptotic pathway, induction of autophagy, stimulation of IFNγ and tumor necrosis factor alpha (TNFα) secretion are some of the mechanisms adopted by the host cells during bacterial infection." (PMID 32987746, 2020). "Interferon-gamma also controls the differentiation CD4Th1 effector T cells which mediate cellular immunity against intracellular bacterial infections." (PMID 33290416, 2020). "CFPA requires antifungal therapy, as mentioned for CCPA, and additional supportive treatment of antibiotics for concurrent bacterial infections, oxygen support, physiotherapy, adjunctive interferon-gamma injections, etc.." (PMID 32498415, 2020). "IFNγ, a Th1 cytokine important in the defense against bacterial infection is upregulated 8.73 ± 0.94 fold." (PMID 32045425, 2020). "BM-AuNPs produced bacterium specific T-cell response and higher production of interferon-gamma (IFN-γ) and interleukin 17 (IL-17), which is responsible for the Th1- and Th17-based T-cell response against bacterial infection." (PMID 31615112, 2019). "IFNγ, a pro-inflammatory cytokine acting against viral and bacterial infections, is one representative source for a pre-conditioning regimen for functional enhancement and upregulation of (pro- and anti-) inflammatory mediators." (PMID 31671899, 2019).
bacterial infection (continued). "NK cells have a key role in the response to intestinal bacterial infections, primarily through production of IFNγ, which can stimulate recruitment of additional NK cells from peripheral blood leading to amplification of the anti-bacterial immune response." (PMID 31130953, 2019). "In murine models of bacterial infection, there is evidence that bacteria can induce pro-inflammatory IFNγ production in ILC3s." (PMID 30984202, 2019). "For the studied Th1 cytokines (IFNγ, TNFα, IL-6, and IL-1β), only IFNγ showed a significant decrease as a consequence of bacterial infection in mechanically ventilated rats." (PMID 31614857, 2019). "With respect to subsequent bacterial infections, however, the most damaging consequences are the IFNγ induced impairment of macrophage phagocytosis and the reduction in neutrophil recruitment due to suppressed IL-8 production." (PMID 30619303, 2018). "IFNγ is vital for host resistance to bacterial infections, while type I IFNs have the opposite effect of increasing host susceptibility." (PMID 28542482, 2017). "Recombinant IFNγ produced a similar in vitro stimulatory effect on LygF1c + d gene expression as seen by bacterial infection, with this cytokine giving a significant additive effect on LygF1c + d expression in infected cells." (PMID 27324690, 2016). "IFNγ is critical in clearing intracellular bacterial infections such as Listeria monocytogenes and Salmonella typhimurium." (PMID 27242968, 2016). "One notion often stated in the literature is that NK cells protect against bacterial infections through their production of IFNγ." (PMID 27295349, 2016). "Interferon-gamma (IFN-γ) protein is one of the inflammatory cytokines which usually result from a response in the human body from a direct invader or latent-virus/bacterial infection." (PMID 27459633, 2016). "Memory-phenotype T cells can also serve as an early source of IFNγ following Lm and other bacterial infections." (PMID 27295349, 2016). "Consistent with the role of Fas-FasL in enhancing immunity to bacterial infections, FasLgld mice produce lower levels of interferon gamma (IFNγ) from splenocytes and have enhanced disease severity compared to wild-type mice." (PMID 25101900, 2014). "These T-cells exhibit a characteristic Th1 response, secreting large amounts of IFNγ required to aid in clearing bacterial infection." (PMID 25386180, 2014). "Conversely, in the spleen, the immune environment was shifted toward a mixed Th1/Th17 response, with increased IFNγ and IL-17A-producing CD4+ T cells, a hallmark of bacterial infection." (PMID 24945934, 2014). "PB1-F2 has been shown to influence the severity of secondary bacterial infection and IFNγ has been shown to inhibit anti-bacterial defense during recovery from influenza virus infection." (PMID 23704945, 2013). "Th1 T cells: CD4+ T cells that express T-helper 1 (Th1)-type cytokines, such as interferon-γ (IFNγ), and facilitate cell-mediated immune responses against viral and bacterial infections." (PMID 23828644, 2013). "Systemic infection by numerous bacterial pathogens elicits potent NK cell activation and IFNγ production, but the mechanisms of NK cell activation during bacterial infections are incompletely understood." (PMID 22072975, 2011). "Furthermore, lymphatic sinus-lining macrophages produce IL-18 in response to bacterial infection, stimulating innate lymphocytes to produce IFNγ, which enhanced macrophage antibacterial function." (PMID 39890933, 2025). "Empirical evidence indicates that interleukin-12 (IL-12) augments the body’s cellular immune response by promoting the differentiation of T-helper 1 (Th1) cells and stimulating the production of interferon-gamma (IFN-γ), thereby effectively counteracting bacterial infections." (PMID 40332240, 2025).
bacterial infection (continued). "Notably, ulcerative colitis sometimes develops following a transient bacterial infection, suggesting that the etiology of this disease involves a failure of IFNγ downregulation after pathogen elimination." (PMID 38962090, 2024). "The correlation of IL-17A- and IFNγ-producing T cells seen in various bacterial infections may be related to the in vivo plasticity of Th17 cells, where cytokine production can switch from predominantly producing IL-17 to IFNγ, thereby resembling Th1 cells." (PMID 39772023, 2024). "In models of bacterial infection, genetic deletion of CD30 or CD 30L leads to a decrease in the long-term ability to control the pathogen that is associated with the loss of long-lived CD4+ T cells secreting IFNg and defective CD8+ T cell memory cells." (PMID 38793771, 2024). "Furthermore, CD64 expression is upregulated on activated neutrophils driven by inflammatory cytokines such as IFNγ and G-CSF or in the presence of bacterial infections." (PMID 37622123, 2023). "Some of their notable functions include:Cytokine production: During intracellular bacterial infection, γδΤ cells have the ability to produce interferon-gamma (IFN-γ) and interleukin 2 (IL-2), exhibiting Th1-like effects similar to helper T lymphocyte type 1 cells." (PMID 37597083, 2023). "Indeed, type I IFNs can exacerbate bacterial infections in mice and humans by directly antagonizing IFNγ signaling." (PMID 38029747, 2023). "Although IFNγ is a well-known cytokine produced during viral and intracellular bacterial infections, the results of this study suggest that IFNγ is produced constantly, even in the absence of foreign antigens, and may prevent excessive ILC2 activation." (PMID 38097562, 2023). "Overall, our findings indicate that bacterial infections that specifically induce IFNγ responses within the lung may restrict SARS-CoV-2 infection." (PMID 38086794, 2023). "In response to intestinal bacterial infections, NK cells can produce IFNG." (PMID 35813827, 2022). "While the principle of immunometabolism has been documented in many different contexts, the most well studied one is during the bacterial infections associated with LPS stimulation (coupled or not to IFNγ stimuli)." (PMID 35154105, 2022). "The production of IFNγ, TLR ligands, TNF-α, PGE2, IL-1β, and IL-6 from T cells or bacterial infection may follow the accumulation MDSCs associated with signal transducer and activator of transcription signaling pathways." (PMID 33212789, 2020). "It suggests that when IFNγ is dominant or pre-existent, as in an intracellular bacterial infection, there is a functional advantage to silencing the antiviral portion of the IFNβ transcriptome, which may be superfluous in this context." (PMID 30918279, 2019). "However, recent studies provided strong evidence for the participation of NK cells in the innate immune response to bacterial infections via the production of pro-inflammatory cytokines, such as interferon gamma (IFN-γ) and tumor necrosis factor-alpha (TNF-α)." (PMID 28706510, 2017). "γδ T cells also produce cytokines IFNγ and TNFα in responses to bacterial infections." (PMID 27560150, 2016). "Similarly, an intrinsic requirement for IFNγ was found to occur during bacterial infection, directing the production and terminal differentiation of myeloid cells." (PMID 27621733, 2016). "Thus, CCR6−CCR2+ defines the GM-CSF/IFNγ-producing population of Th17 cells that arise in a model of persistent extracellular bacterial infection." (PMID 26511769, 2015). "However, they have also been shown to be important in the early immune response and subsequent elimination of bacterial infections, are their activity becomes enhanced in the presence of cytokines such as IL-12 and interferon γ (IFNγ)." (PMID 25386180, 2014).
bacterial infection (continued). "IRGM is known to play a protective role against bacterial infection favoring IFNγ-mediated autophagy elimination of Mycobacterium bovis in macrophages and anti-bacterial autophagy responses in epithelial cells against Salmonella thyphymurium and adherent-invasive Escherichia coli." (PMID 22174682, 2011). "NK cells are the major source of IFNγ production early after viral and bacterial infections." (PMID 22072975, 2011). "Indeed, knockout SPP1-/- mice have shown significantly impaired Th1 immunity to viral and bacterial infections with diminished production of interleukin-12 (IL-12) and interferon-gamma (IFN-γ) and elevated production of interleukin-10 (IL-10)." (PMID 19765294, 2009). "Similarly, it has been shown that CD8+ lymphocytes infiltrated into the lungs following adenoviral infection were important to, through the release of IFNγ, confer a primed immunity phenotype to AMs, resulting in robust host resistance against heterologous bacterial infection." (PMID 35062301, 2022). "Although overall mechanisms remain elusive, it is known that bacterial infections activate NF-kB pathway via toll-like receptors and airway epithelial cells, which, in turn, promotes transcription of pro-inflammatory substances like IL-6, IL-8, and interferon gamma (IFN-γ)." (PMID 36466839, 2022). "Interestingly, in mice, miR-29 was shown to suppress the interferon-gamma (IFN-γ) production by targeting IFN-γ mRNA directly, and miR-29 knockdown mice initiated more potent innate and type 1 helper T cell adaptive responses to intracellular bacterial infection." (PMID 31817907, 2019). "The existence of multiple intracellular cod g-type lysozymes with no or very low enzyme activities, and the demonstrated modulation of lysozyme gene expression by bacterial infection and IFNγ, allows speculations about a possible role for lysozymes in the process of selective autophagy of bacteria." (PMID 27324690, 2016). "Collectively, our results suggest that the short-term benefit of ADAM17 inhibition might lead to enhanced secretion of IFNγ, while long-term inhibition of ADAM17 might be detrimental and could increase the risk of bacterial infection due to drastic decrease in soluble TNFα." (PMID 26683521, 2015). "Our previous data demonstrated that IFNγ is an important modifier of hematopoiesis during bacterial infection, so we also addressed whether the changes in hematopoietic progenitor and stem cells were IFNγ-dependent, by examining these populations in IFNγR-deficient mice during acute infection." (PMID 22194881, 2011). "Here, we show an impaired expression of IFNγ in human macrophages treated with GapCARINH and in mice depleted for Carinh upon viral stimulus, suggesting a potential function for CARINH upon bacterial infection." (PMID 39773901, 2025). "Among the diverse repertoire of cytokines, interferon-gamma (IFN-γ) has a key role, contributing to protection from viral and bacterial infections and regulating effector cells in both innate and adaptive immunity." (PMID 39203954, 2024). "Here we explored the mechanisms by which concurrent bacterial infection protects against SARS-CoV-2 and show that IFNγ is an essential mediator of BCG conferred protection in vivo." (PMID 38086794, 2023). "IFNG is a type II IFN cytokine critical to both innate and adaptive immunity and which helps fight against viral and bacterial infections." (PMID 37630519, 2023). "uPAR expression is upregulated on endothelial and hematopoietic cells during bacterial infection and in response to pro-inflammatory cytokines [e.g., tumor necrosis factor alpha (TNF-α), interferon gamma (IFN-γ), and interleukin 2 (IL-2)]." (PMID 35757694, 2022). "IFNγ induces the CXC chemokines, MIG, IP-10 and I-TAC, from multiple cell types to attract T cells and to promote host resistance to bacterial infections." (PMID 33571211, 2021).